LINC01016 (long independently transcribed non-coding RNA 1016)
Gene: Long non-coding RNA gene on chromosome 6 (33,834,487 to 33,983,208, reverse strand). Ensembl gene ENSG00000249346.
Diseases named in the same sentence as LINC01016 in open-access papers:
LINC01016 is named in the same sentence as 8 diseases in open-access papers, as found by Europe PMC text mining. Sharing a sentence is not in itself a finding about the gene and the disease. The quoted sentences say what the papers report.
breast carcinoma (5 papers, 2016 to 2023). "In addition, LINC01016 is a direct target of ERα, associated with survival prognosis of breast cancer." (PMID 33216456, 2021). "In conclusion, we identified a novel autophagy‐related prognostic risk model consisting of 11 lncRNAs (U62317.4, LINC01016, LINC02166, C6orf99, LINC00992, BAIAP2‐DT, AC245297.3, AC090912.1, Z68871.1, LINC00578 and LINC01871) in breast cancer." (PMID 33216456, 2021). "Herein, we found that LINC01016 was overexpressed in endometrial cancer tissues, consistent with LINC01016 expression in breast cancer." (PMID 29467441, 2018). "LINC01016 also showed prognostic significance in relation to breast cancer survival." (PMID 29467441, 2018). "The predicting value of 11 sARLNRs (U62317.4, LINC01016, LINC02166, C6orf99, LINC00992, BAIAP2-DT, AC245297.3, AC090912.1, Z68871.1, LINC00578, and LINC01871) was also identified in breast cancer." (PMID 34414116, 2021). "So far, among these 11 autophagy‐related lncRNAs, only LINC01016 and LINC00578 have been studied in breast cancer or other cancers." (PMID 33216456, 2021). "However, some of them, notably DSCAM-AS1, LINC01016, LINC00925, KRTAP5-AS1, were quite specific to breast cancer cell lines." (PMID 26621851, 2016).
endometrial carcinoma (3 papers, 2018 to 2025). A malignant tumor arising from the epithelium that lines the cavity of the uterine body. "LINC01016 has been reported to promote cell migration and invasion in endometrial carcinoma by acting as a sponge absorber, similar to ceRNA." (PMID 39881131, 2025). "In endometrial carcinoma, LINC01016 has been shown to function as a ceRNA, and upregulated LINC01016 promoted proliferation, migration, and invasion, which is concordant with our findings." (PMID 37550275, 2023). "LINC01016 and miR-302a-3p/miR-3130-3p made up two bidirectional regulatory feedback loops that mediated the malignant phenotype of endometrial cancer cells via NFYA and its target SATB1." (PMID 29467441, 2018). "LINC01016 was substantially upregulated in endometrial cancer tissues, and LINC01016 silencing abolished the malignant behavior of endometrial cancer cells." (PMID 29467441, 2018). "LINC01016 was more highly expressed in endometrial cancer tissues than in unaffected tissues detected by quantitative real-time polymerase chain reaction (qRT-PCR) and in situ hybridization (ISH)." (PMID 29467441, 2018). "Considering recent research describing the role of ceRNAs in neoplasia, we hypothesized that LINC01016 might function as a ceRNA in endometrial cancer by competitively binding with miR-302a-3p/miR-3130-3p and promoting the downstream degradation of mRNAs." (PMID 29467441, 2018). "Therefore, we postulated that LINC01016 was a putative oncogene in endometrial cancer." (PMID 29467441, 2018). "Therefore, LINC01016 promoted the malignant behavior of endometrial cancer cells." (PMID 29467441, 2018). "Here, we found that LINC01016 promoted oncogenic processes by targeting miR-302a-3p and miR-3130-3p and inducing the overexpression of NFYA, thus affecting SATB1 expression in endometrial cancer cells." (PMID 29467441, 2018). "Conversely, miR-302a-3p/miR-3130-3p could regulate the expression of LINC01016, forming two negative feedback loops, and influence the malignant phenotype of endometrial cancer cells." (PMID 29467441, 2018).
breast tumors (1 paper, 2024). "The lncRNA GATA3-AS1 has previously been implicated in resistance to NAC, while LINC01016 has been shown to be specifically expressed in estrogen receptor-positive breast tumors." (PMID 39125649, 2024).
gastric cancer (1 paper, 2025). A primary or metastatic malignant neoplasm involving the stomach. "Before investigating the relationship between EIF4A3 and LINC01016 in the progression of gastric cancer, we first evaluated the role of EIF4A3 in this carcinogenic context." (PMID 39881131, 2025). "LINC01016 could affects downstream protein expression by binding to EIF4A3 and promotes the progression of gastric cancer." (PMID 39881131, 2025). "Subsequently, evaluating the expression of LINC01016 in human normal gastric epithelial cell line GES-1 and gastric cancer cell lines HGC27, BGC823, MKN45, MGC803 revealed that LINC01016 was notably upregulated in GC cell lines compared with GES-1, especially HGC27 and BGC823." (PMID 39881131, 2025).
lymph node metastasis (1 paper, 2025). "In the present study, we showed that the expression of the long intergenic noncoding RNA 01016 (LINC01016) is significantly higher in GC tissues with lymph node metastasis (LNM) than those without LNM." (PMID 39881131, 2025).
thyroid cancer (1 paper, 2025). "While LINC01016 is considered an indicator of poor prognosis in breast and thyroid cancer, the mechanism remains unknown." (PMID 39881131, 2025).
cancer (6 papers, 2018 to 2025). A tumor composed of atypical neoplastic, often pleomorphic cells that invade other tissues. "Knockdown of LINC01016 in company with miR-302a-3p/miR-3130-3p overexpression significantly restrained the malignant phenotype of cancer cells in vitro and ablated tumor growth in vivo." (PMID 29467441, 2018). "MiRNAs could inhibit LINC01016 transcription, forming two reciprocal repression cycles, which influence cancer cells’ biological behavior." (PMID 34150649, 2021). "The analysis revealed the highest upregulation of PGR and LINC01016 genes in ER+ compared to ER− cancers (regardless of HSF1 status)." (PMID 34783649, 2021). "However, the molecular mechanism by which LINC01016 is upregulated in these cancers has not been elucidated." (PMID 37550275, 2023).
tumor (4 papers, 2018 to 2025). "High LINC01016 expression was associated with the degree of tumor differentiation, depth of invasion, and LNM." (PMID 39881131, 2025). "LINC01016 is found to be located on chromosome 6q21.31, assembles with a transcript length of 3165 bp, and is frequently amplified in tumor tissues." (PMID 39881131, 2025). "The expression of MIR100HG, MNX1_AS1, and LINC01016 increased in the later tumor stages (Stage III and Stage IV)." (PMID 38534739, 2024). "LINC01016 is located on chromosome 6q21.31, and its upregulation has been detected in various tumor types." (PMID 37550275, 2023). "In summary, when LINC01016 was knocked down, tumor proliferation, invasion, and distant metastasis were significantly inhibited, suggesting that LINC01016 could be used as a potential therapeutic target for TNBC." (PMID 37550275, 2023). "In addition, we performed the co-transfection of LINC01016 and miR-302a-3p/miR-3130-3p, which verified that miR-302a-3p/miR-3130-3p functionally reversed the tumor-promoting effect of LINC01016 on cell proliferation, cell cycle regulation, apoptosis, migration, and invasion." (PMID 29467441, 2018). "When LINC01016 is overexpressed, the binding of EIF4A3 and MMP9 mRNA is blocked, and NMD is inhibited, leading to the upregulation of MMP9, thus promoting tumor progression." (PMID 39881131, 2025). "We determined that LINC01016 can blocks the binding of EIF4A3 to MMP9 mRNA, thereby inhibiting EIF4A3-mediated nonsense-mediated RNA decay (NMD), increasing MMP9 mRNA level and protein expression levels to promote tumor progression." (PMID 39881131, 2025). "LINC01016 blocks the binding of EIF4A3 to MMP9 mRNA, thereby inhibiting EIF4A3-mediated NMD, leading to increased MMP9 mRNA and protein expression, and promoting tumor progression." (PMID 39881131, 2025). "To elucidate whether LINC01016 could affect tumor growth and metastasis in vivo, we injected LINC01016 stable-knockdown HGC27 cells into the subcutaneous and caudal veins of male nude mice to construct a xenograft tumor model." (PMID 39881131, 2025). "We speculated that LINC01016 may increase the expression of MMP9 through EIF4A3 and played a tumor-promoting role." (PMID 39881131, 2025). "Moreover, ISH and IHC were performed to detect the expression of LINC01016, miR-302a-3p/miR-3130-3p, NFYA, and SATB1 in xenograft tumor tissues formed by Ishikawa cells." (PMID 29467441, 2018). "Whether LINC01016 can participate in tumor biological behavior through binding protein has not been reported." (PMID 39881131, 2025).